TMEM70 (transmembrane protein 70)
Description:
Scaffold protein that participates in the c-ring assembly of mitochondrial ATP synthase (F(1)F(0) ATP synthase or complex V) by facilitating the membrane insertion and oligomer formation of the subunit c/ATP5MC1 through its interaction. Therefore, participates in the early stage of mitochondrial ATP synthase biogenesis and also protects subunit c/ATP5MC1 against intramitochondrial proteolysis. In addition, binds the mitochondrial proton-transporting ATP synthase complexes I and may play a role in the stability of its membrane-bound subassemblies.
Synonyms: MC5DN2; FLJ20533
Tractability: Antibody: UniProt predicts a signal peptide or a membrane-spanning region. PROTAC: ubiquitination databases record sites on it; its protein half-life has been measured.
Gene: Protein-coding gene on chromosome 8 (73,972,437 to 73,982,783, forward strand). Ensembl gene ENSG00000175606.
Subcellular location: Mitochondrion inner membrane
Subcellular location (Human Protein Atlas): Mitochondria; Nucleoplasm
Gene Ontology:
Molecular function: mitochondrial proton-transporting ATP synthase complex binding; protein binding; protein-macromolecule adaptor activity
Biological process: mitochondrial proton-transporting ATP synthase complex assembly; mitochondrial respiratory chain complex I assembly; protein complex oligomerization; protein homooligomerization
Cellular component: mitochondrial crista; mitochondrial inner membrane; mitochondrial membrane; mitochondrion
Genetic constraint (gnomAD): Loss-of-function variants: 19 observed, 20.27 expected, observed/expected ratio (o/e) 0.94, 90% interval 0.65 to 1.38. The upper end of that interval is the gene's LOEUF score, 1.38, which puts it in group 5 of 6, group 1 being the genes least tolerant of losing a copy. Missense variants: 344 observed, 322.1 expected, observed/expected ratio (o/e) 1.07, 90% interval 0.98 to 1.17. Synonymous variants: 141 observed, 125.99 expected, observed/expected ratio (o/e) 1.12, 90% interval 0.98 to 1.29.
Gene-disease validity (ClinGen):
ClinGen rates the evidence that TMEM70 causes each of these diseases.
mitochondrial disease (autosomal recessive): Definitive.
Homologues: Orthologues: chimpanzee TMEM70 (98% identical), macaque TMEM70 (87% identical), guinea pig TMEM70 (68% identical), pig TMEM70 (68% identical), mouse Tmem70 (60% identical), rat Tmem70 (59% identical), rabbit LY96 (53% identical), dog TMEM70 (52% identical), tropical clawed frog tmem70 (40% identical), zebrafish tmem70 (39% identical), Drosophila melanogaster CG7506 (28% identical), Caenorhabditis elegans F32D8.5 (20% identical).
Diseases named in the same sentence as TMEM70 in open-access papers:
TMEM70 is named in the same sentence as 38 diseases in open-access papers, as found by Europe PMC text mining. Sharing a sentence is not in itself a finding about the gene and the disease. The quoted sentences say what the papers report.
cardiomyopathy (6 papers, 2015 to 2022). A disease of the heart muscle or myocardium proper. "The most common defects involve TMEM70, including a Roma TMEM70 founder mutation causing lactic acidosis and cardiomyopathy 58, although encephalopathy and cataracts have been reported in other populations." (PMID 27659608, 2017). "Other mitochondrial diseases with cardiomyopathies include Barth syndrome, Sengers syndrome, TMEM70-related mitochondrial complex V deficiency, and Friedreich ataxia." (PMID 27504452, 2016). "Meanwhile, the candidate gene TMEM70 causing a complex V deficiency with morphological stigmata, cardiomyopathy, and metabolic crises frequently occurring in families of Roma ethnic background had been described." (PMID 26550569, 2015). "The TMEM70 gene produces a phenotype of neonatal onset, cardiomyopathy, facial dysmorphism, lactic acidosis, and 3-methylglutaconic aciduria." (PMID 33426505, 2020). "At present, research related to TMEM70 mainly focuses on cardiomyopathy and pulmonary hypertension." (PMID 32874785, 2020). "Other disorders in this group that might be associated with cardiomyopathy are caused by mutations in DNAJC19, TMEM70, and AGK." (PMID 27504452, 2016).
lactic acidosis (4 papers, 2017 to 2025). Metabolic acidosis characterized by the accumulation of lactate in the body. "Transmembrane protein 70 (TMEM70) deficiency (TMEM70, autosomal recessive, MIM #614052) is the most frequently reported cause of nuclear‐encoded ATP synthase deficiency, resulting in a neonatal encephalocardiomyopathy with lactic acidosis and hyperammonaemia." (PMID 38872485, 2025).
pulmonary hypertension (4 papers, 2015 to 2020). Increased pressure within the pulmonary circulation due to lung or heart disorder. "Three of the 4 patients developing pulmonary hypertension died during follow-up: they were affected by MELAS, TMEM70 and tRNAGlu mutation." (PMID 32736646, 2020).
Barth syndrome (2 papers, 2016 to 2020). Barth syndrome (BTHS) is an inborn error of phospholipid metabolism characterized by dilated cardiomyopathy (DCM), skeletal myopathy, neutropenia, growth delay and organic aciduria. "CVI was confirmed in all patients diagnosed with TMEM70 deficiency and Barth syndrome; MELAS syndrome was associated with heart disease in 62% of the children and NARP in 25%." (PMID 32736646, 2020). "TMEM70 and Barth syndrome were systematically associated with CVI, but prevalence also proved high in MELAS syndrome." (PMID 32736646, 2020). "MELAS syndrome due to MTTL1 A3243G mutation was the most frequent finding (9%), followed by TMEM70 (6%), NARP and Barth syndrome (5% each)." (PMID 32736646, 2020).
developmental delay (2 papers, 2019 to 2021). "We identified novel compound heterozygous TMEM70 variants in a Japanese patient who had hyperlactacidemia, metabolic acidosis, hyperalaninemia, developmental delay, undescended testicle, and left ventricular noncompaction." (PMID 30899493, 2019). "Additionally, ARFGEF2, MIPEP, NONO, SH2B1, and TMEM70 led to LVNC complicating developmental delay." (PMID 34819141, 2021).
breast carcinoma (1 paper, 2021). "In accordance with the gene expression levels, the protein levels of ZDHHC9, PCMT1, TMEM70 were significantly higher in breast cancer, and the protein levels of IRF2, KCNJ11 were higher in normal tissues." (PMID 34956313, 2021).
congenital myasthenic syndrome (1 paper, 2018). Congenital myasthenic syndrome (CMS) is a group of genetic disorders of impaired neuromuscular transmission at the motor endplate characterized by fatigable muscle weakness. "An isolated ATP synthase deficiency due to the pathogenic variant 317-2A>G in the TMEM70 gene and congenital myasthenic syndrome due to the deletion of 1267delG in the CHRNE gene was referred to later." (PMID 29678161, 2018).
inflammatory bowel disease (1 paper, 2025). A spectrum of small and large bowel inflammatory diseases of unknown etiology. "NADH dehydrogenase [ubiquinone] flavoprotein 2, hydroxymethylglutaryl‐CoA synthase 9, pyruvate carboxylase, apoptosis‐inducing factor 1, and transmembrane protein 70 with inflammatory bowel disease were identified as protective factors." (PMID 40837128, 2025).
MELAS syndrome (1 paper, 2020). MELAS (Mitochondrial myopathy, encephalopathy, lactic acidosis, and stroke) syndrome is a rare progressive multisystemic disorder characterized by encephalomyopathy, lactic acidosis, and stroke-like episodes. "Heart disease resulted more common in males and in children with specific aetiologies (Barth, TMEM70 and MELAS syndromes)." (PMID 32736646, 2020).
Mitochondrial myopathy (1 paper, 2021). "Mutations in POLG (one case), TSEN54 (one case), TMEM70 (one case), and KARS (one case) were eventually identified only after the biochemical data, as the histopathology study did not clearly indicate a mitochondrial myopathy." (PMID 34675869, 2021).
multiple mitochondrial dysfunctions syndrome 4 (1 paper, 2025). Any fatal multiple mitochondrial dysfunctions syndrome in which the cause of the disease is a mutation in the ISCA2 gene. "The resulting syndromes varied, with the most common being multiple mitochondrial dysfunction syndrome 4 (ISCA2) in 13.8%, achalasia addisonian alacrima syndrome (AAAS) in 8.6%, and mitochondrial complex I, III, V, or IV syndromes (TMEM70, MT-ND5, and ATP5MD, among others) in 12.9%." (PMID 40868553, 2025).
status epilepticus (1 paper, 2024). Status epilepticus is defined as a continuous seizure lasting more than 30 min, or two or more seizures without full recovery of consciousness between any of them. "A patient with an ATP5PO mutation encoding OSCP recently died from refractory status epilepticus, and a separate case involving a TMEM70 mutation also presented with status epilepticus." (PMID 39850733, 2024).
mitochondrial disease (4 papers, 2016 to 2025). "Given the known role of TMEM70, mutations in TMEM70 lead to oxidative phosphorylation (OXPHOS) deficiencies linked to many mitochondrial diseases that present as neonatal mitochondrial encephalo-cardiomyopathy in humans." (PMID 34359920, 2021). "Mutations in TMEM70 (mitochondrial complex V deficiency), encoding a protein involved in the insertion of ATP synthase (complex V) into the mitochondrial membrane, result in multi-organ mitochondrial disease with hypertrophic cardiomyopathy." (PMID 27504452, 2016). "In addition, 3-methylglutaconate and 3-methylglutarate, derived from leucine metabolism, showed 100 % sensitivity and specificity in distinguishing TMEM70-deficient patients from controls, highlighting their diagnostic potential for screening selected mitochondrial diseases." (PMID 41477503, 2025).
cardiovascular disease (1 paper, 2022). "We noticed that six DEPs (Pltp, Pir, Thbs1, Tmem70, Hacd2, and Ppm1k) closely related to cardiovascular disease were either significantly downregulated or upregulated." (PMID 36312255, 2022).
infection (1 paper, 2020). The state of being infected such as from the introduction of a foreign agent such as serum, vaccine, antigenic substance or organism. "This paradigm also seems to apply to TMEM70 deficiency, in which heart involvement is a constant feature but per se a stable one; acute decompensation may develop as consequence of metabolic crisis or severe infections." (PMID 32736646, 2020).
movement disorder (1 paper, 2026). Neurological conditions resulting in abnormal voluntary or involuntary movement, which may impact the speed, fluency, quality and ease of movement. "HVA was particularly elevated (> 2SD above control mean) in the patient with TMEM70-related disease, presenting with mild movement disorder sequelae following severe neonatal-onset." (PMID 41549148, 2026).
TMEM70 also shares sentences with these, for which no sentence is quoted: Sengers syndrome (2 papers); 3-methylglutaconic aciduria (1); cataract (1); deficiencies (1); Encephalopathy (1); External ophthalmoplegia (1); Friedreich ataxia (1); glycogen storage diseases (1); heart disease (1); Hepatic steatosis (1); hyperalaninemia (1); Hyperammonemia (1); hypomyelinating leukodystrophy (1); hypospadias (1); Leigh syndrome (1); metabolic acidosis (1); Mitochondrial complex deficiency (1); mitochondrial complex V deficiency (1); myopathy (1); neuronal ceroid lipofuscinosis (1); pontocerebellar hypoplasia type 1B (1); vitiligo (1).